NFIL3 (nuclear factor, interleukin 3 regulated)
Diseases named in the same sentence as NFIL3 in open-access papers (continued):
Sharing a sentence is not in itself a finding about the gene and the disease.
ovarian carcinoma (4 papers, 2011 to 2024). A malignant neoplasm originating from the surface ovarian epithelium. "The expression and functional significance of NFIL3 have been associated with ovarian cancer and could also be a potential biomarker for this type of cancer." (PMID 39765744, 2024). "CCK8 assays provided clear evidence that NFIL3 overexpression significantly inhibited the proliferation of ovarian cancer (OC) cells, while the use of sgRNA targeting NFIL3 promoted OC cell proliferation." (PMID 38356719, 2024). "Scratch wound healing assays demonstrated that NFIL3 overexpression suppressed cell migration, while NFIL3 knockdown enhanced the migratory ability of ovarian cancer cells." (PMID 38356719, 2024). "The selection of ovarian cancer as a model for studying NFIL3 was driven by several compelling factors." (PMID 38356719, 2024). "In ovarian cancer, NFIL3 was found to exert significant effects on cell proliferation, migration, and immune cell infiltration." (PMID 38356719, 2024). "The results indicated that NFIL3 overexpression increased the capacity of ovarian cancer cells to attract Jurkat T cells, whereas NFIL3 knockdown had the opposite effect, inhibiting the ability of cancer cells to attract Jurkat T cells." (PMID 38356719, 2024). "To assess the potential impact of NFIL3 on the biological processes of ovarian cancer (OC) cells, we conducted an analysis of NFIL3 gene expression in various human ovarian cancer cell lines using western blot analysis." (PMID 38356719, 2024). "While previous research has predominantly focused on its role in immune regulation, the connection between NFIL3 expression and its biological function in various human cancers, including ovarian cancer, has remained largely unexplored." (PMID 38356719, 2024). "RBP4, a tumor suppressor in ovarian cancer, is negatively regulated by NFIL3 and has lower gene expression value in NG group." (PMID 27586240, 2016). "In the context of ovarian cancer, we validated the expression and functional relevance of NFIL3." (PMID 38356719, 2024). "Similarly, transwell assays confirmed that NFIL3 knockdown significantly promoted the migration ability of ovarian cancer cells." (PMID 38356719, 2024). "Additionally, we assessed NFIL3 protein expression using paraffin sections from 12 ovarian normal controls and 12 ovarian cancer samples, and the immunohistochemical scores were assessed by three pathologists." (PMID 38356719, 2024). "Experimental investigations involving scratch assays, transwell assays, and assessments of cell proliferation in ovarian cancer cells have provided indications that NFIL3 may exert influence over cell migration and proliferation processes." (PMID 38356719, 2024). "To investigate the mechanistic involvement of NFIL3 in ovarian cancer regulation, we conducted KEGG enrichment analysis on the overlap of potential targets of NFIL3 and genes exhibiting differential expression between normal ovarian tissue and ovarian cancer tissue." (PMID 38356719, 2024). "Secondly, the specific role of NFIL3 in ovarian cancer had not been previously investigated." (PMID 38356719, 2024).
Stroke (4 papers, 2022 to 2024). Sudden impairment of blood flow to a part of the brain due to occlusion or rupture of an artery to the brain. "ROC curve analysis indicated that OTUD1 and NFIL3 could predict stroke occurrence with a certain degree of accuracy, while OSM could not." (PMID 37695739, 2023).
thyroid cancer (4 papers, 2018 to 2022). "NFIL3 also promoted thyroid cancer proliferation and induced EMT, cell migration and experimental metastasis of colorectal cancer cells." (PMID 35180863, 2022).
triple-negative breast carcinoma (4 papers, 2024 to 2025). An invasive breast carcinoma which is negative for expression of estrogen receptor (ER), progesterone receptor (PR), and human epidermal growth factor receptor 2 (HER2). "Furthermore, the level of NFIL3 protein was significantly increased in triple-negative breast cancer (TNBC) and was associated with poorer prognosis." (PMID 38500661, 2024). "Additionally, NFIL3 has been implicated in the progression of triple negative breast cancer (TNBC) by activating NF-κB signaling." (PMID 38356719, 2024). "These are interesting findings, since other authors have shown that NFIL3 increased tumor progression of triple-negative breast cancer type by suppressing NFKB inhibitor alpha (NFKBIA) transcription." (PMID 39765744, 2024). "Hence, the present study aimed to analyze genes associated with the immune system such as TNFAIP6, IFRD1, IFITM2, IFNGR1, IRF6, and NFIL3 in cell lines such as control MCF-10F (Ct), a triple-negative breast cancer cell line, estrogen (E), Alpha3 (A3), Alpha5 (A5), and Tumor2 (T2)." (PMID 39765744, 2024).
asthma (3 papers, 2019 to 2025). "Future studies should aim to address how specific clock genes (e.g., Nr1d1 and Nfil3) play an essential role in asthma pathophysiology using chronotherapeutic approaches to delineate observed sex-based differences in severe asthma." (PMID 37664635, 2023). "Similarly, hsa-miR-3059-5p, Asthma, Diabetes Mellitus, NFIL3, Simvastatin, and Cadmium have an interaction relationship centred on CX3CR1." (PMID 40461634, 2025). "However, NFIL3 on the other hand is known for its anti-inflammatory role in asthma." (PMID 37664635, 2023). "Based on the close functional relationship between NFIL3 and DBP, it is safe to assume they may be significant candidate genes to devise options for treating patients with severe asthma." (PMID 37664635, 2023). "Small molecules that target NFIL3 can be of potential benefit to attenuate HDM-induced allergic airway inflammation in females with and without steroid-resistant asthma phenotype." (PMID 37664635, 2023).
atherosclerosis (3 papers, 2024 to 2025). A disease characterized by the build-up of fatty material and calcium deposition in the arterial wall resulting in partial or complete occlusion of the arterial lumen. "The pro-inflammatory effects of NFIL3 have been associated with atherosclerosis in patients with rheumatoid arthritis." (PMID 41009355, 2025). "NFIL3 has been implicated in the progression of atherosclerosis through the regulation of inflammatory responses, macrophage polarization, and lipid metabolism." (PMID 41009355, 2025).
diabetes (3 papers, 2014 to 2025). "Here, we give an overview of NFIL3 transcriptional regulatory circuits and discuss emerging areas of NFIL3 research regarding cancer and diabetes." (PMID 26539561, 2014). "A list of 15 known clock genes from the primary (Arntl, Clock, Npas2, Per1, Per2, Per3, Cry1, Cry2), secondary (Nrd1d1, Nr1d2, Rora, Rorb, Rorc), and accessory TTFL loops (Nfil3, Dbp) were selected to investigate the effect of diabetes on their rhythmic expression." (PMID 38039846, 2024). "Very recently, NFIL3 has emerged as a novel factor that might promote human diseases such as diabetes and cancer." (PMID 26539561, 2014). "Taken as a whole, the ability of Nfil3 to regulate metabolism is becoming increasingly evident and suggests that it may have a role in diabetes." (PMID 26539561, 2014). "Finally, the regulation of NFIL3 will be an exciting new frontier for future research and will have broad implications for cellular processes discussed in this review as well as human diseases such as cancer and diabetes." (PMID 26539561, 2014).
glioma (3 papers, 2016 to 2026). A benign or malignant brain and spinal cord tumor that arises from glial cells (astrocytes, oligodendrocytes, ependymal cells). "We also proposed some testable hypotheses on the roles of AHR and NFIL3 in glioma carcinogenesis which are worthy of further experimental investigations." (PMID 27586240, 2016). "According to our inferred differential networking information and previously reported signalling knowledge, we suggested testable hypotheses on the roles of AHR and NFIL3 in glioma carcinogenesis." (PMID 27586240, 2016). "Based on our inferred differential networking information and the previously reported signalling knowledge around our signature genes, we generated testable hypotheses on the roles of AHR and NFIL3 in glioma carcinogenesis." (PMID 27586240, 2016). "We investigated the relevance of the three-TF signature to regulation mechanisms of glioma carcinogenesis and suggested AHR, NFIL3 and ZNF423 as promising biomarkers for not only glioma molecular subtype diagnosis but also clinical treatment." (PMID 27586240, 2016). "In this study, we analysed 6 public transcriptome glioma data sets and identified three glioma prognosis-related transcription factors, AHR, NFIL3 and ZNF423." (PMID 27586240, 2016). "We revealed a novel three-transcription-factor signature including AHR, NFIL3 and ZNF423 for glioma molecular subtypes." (PMID 27586240, 2016). "The expression values of AHR, NFIL3 and ZNF423 across glioma subtypes are significantly different." (PMID 27586240, 2016). "Therefore, we checked if these three transcription factors (AHR, NFIL3 and ZNF423) could be a glioma prognosis-related signature by measuring its clinical relevance with NMF clustering method and survival analysis." (PMID 27586240, 2016).
gout (3 papers, 2022 to 2023). A condition characterized by painful swelling of the joints, which is caused by deposition of urate crystals. "Silencing of NFIL3 reduces inflammatory injury in mice with acute gouty arthritis through inhibiting neutrophil autophagy and the formation of NETs." (PMID 36532016, 2022). "In addition, NFIL3 can aggravate the inflammatory response in gout by stimulating neutrophil autophagy and the formation of NETs through REDD1/mTOR." (PMID 36532016, 2022). "Nuclear factor, interleukin 3 regulated (NFIL3), which is highly expressed in neutrophils of patients with gout, promotes its transcription by binding to the REDD1 promoter, which enhances autophagy and NET formation by inhibiting the mTOR pathway, to promote inflammatory responses." (PMID 35464445, 2022).
Hepatic steatosis (3 papers, 2024 to 2025). Steatosis is a term used to denote lipid accumulation within hepatocytes. "This study explores the role of nuclear factor interleukin 3 (Nfil3) in metabolic dysfunction-associated fatty liver disease (MASLD) development, revealing sex-specific effects and gut microbiota influence on bile acid metabolism." (PMID 39048678, 2024). "Therefore, inhibiting NFIL3 reduces the expression of genes related to lipid droplet association and fat uptake in hepatocytes, decelerates de novo lipogenesis, and alleviates HFD-induced hepatic steatosis and liver injury." (PMID 40177474, 2025). "Targeted knockout of the NFIL3 gene significantly enhances the activity of adenosine monophosphate-activated protein kinase (AMPK) in the liver and increases the abundance of the AMPK β1 subunit, thereby improving hepatic steatosis and liver function in mice." (PMID 40177474, 2025).
Hypertension (3 papers, 2020 to 2024). The presence of chronic increased pressure in the systemic arterial system. "Here, we found the significant association of ADM, EDN1, ANGPTL4, USP8, NFIL3, MSR1, and CEBPD genes with hypertension." (PMID 35205232, 2022). "Interestingly, recent genome-wide meta-analysis also identified Nfil3 as significant potential gene target for hypertension." (PMID 38501595, 2024). "NFIL3 could be a possible target, as it is a circadian clock regulator gene that might be involved in hypertension and lipid metabolism." (PMID 35205232, 2022). "From 50 DEGs, we ranked 7 hypertension-related genes (p-value < 0.05): ADM, ANGPTL4, USP8, EDN, NFIL3, MSR1, and CEBPD." (PMID 35205232, 2022). "ADM, EDN1, ANGPTL4, NFIL3, MSR1, CEBPD, and USP8, based on their FDR values (<0.05, p-values (≤0.05)), were the top DEGs for hypertension." (PMID 35205232, 2022).
Insulin resistance (3 papers, 2020 to 2025). Increased resistance towards insulin, that is, diminished effectiveness of insulin in reducing blood glucose levels. "NFIL3 overexpression in the liver promotes gluconeogenesis, disrupts lipid metabolism and insulin signalling, induces insulin resistance in the liver and muscles, and increases the risk of metabolic syndrome." (PMID 40177474, 2025).
liver fibrosis (3 papers, 2024 to 2025). "Nfil3 gene deletion decreased HFD-induced liver fibrosis and inflammation in male MASLD mice." (PMID 39048678, 2024).
lymphoma (3 papers, 2014 to 2024). A malignant (clonal) proliferation of B- lymphocytes or T- lymphocytes which involves the lymph nodes, bone marrow and/or extranodal sites. "Utilizing the HPA database, we conducted an examination of NFIL3 protein levels in various tumors, revealing a decrease in NFIL3 levels in lung, colon cancers and lymphoma." (PMID 38356719, 2024). "As an alternative, we found that NFIL3 regulates Tox expression in EL4 cells, a mouse lymphoma cell line." (PMID 25310240, 2014). "NFIL3 has been shown to directly bind to the TOX promoter in a mouse lymphoma cell line and ectopic expression of TOX restored ILCs in the absence of NFIL3, though with low efficiency." (PMID 26556952, 2015).
rheumatoid arthritis (3 papers, 2022 to 2025). A chronic, systemic autoimmune disorder characterized by inflammation in the synovial membranes and articular surfaces. "We visualized the hsa05323 rheumatoid arthritis pathway using the online database Pathview and observed that the various proinflammatory cytokines, chemokines, and matrix metalloproteinases were highly expressed in the NFIL3-high group." (PMID 36439145, 2022). "However, the relationship between rheumatoid arthritis (RA) and NFIL3 remains largely unknown." (PMID 36439145, 2022). "Moreover, we confirmed high NFIL3 expression in RA synovial tissue using the GEO dataset and identified NFIL3 coexpression genes, the potential pathways, and molecular functions, which were mainly involved in the IL-17 signaling pathway, lipid metabolism, and rheumatoid arthritis pathways." (PMID 36439145, 2022).
Alzheimer disease (2 papers, 2012 to 2024). A progressive, neurodegenerative disease characterized by loss of function and death of nerve cells in several areas of the brain leading to loss of cognitive function such as memory and language. "We believe these characteristics of E4BP4/ NFIL3 are very relevant to our findings because the importance of immunological and inflammatory processes in the pathogenesis and therapy of Alzheimer's disease is well documented." (PMID 22947103, 2012).
colon cancer (2 papers, 2014 to 2024). "Furthermore, NFIL3 may hinder the recruitment of Proline Acid Rich (PAR) transcription factors to pro-apoptotic genes in colon cancer, as indicated by previous studies." (PMID 38356719, 2024). "In addition to colon cancer, NFIL3 may have a role in esophageal cancer as irradiation of esophageal cancer cell lines leads to a loss in NFIL3 expression." (PMID 26539561, 2014). "NFIL3 was found to repress the pro-apoptotic, BH3-only gene BGL-GS (also known as BCL2-like 14) in colon cancer cells." (PMID 26539561, 2014). "Mechanistically, NFIL3 has been found to block FOXO1 recruitment to certain tumor suppression-related genes and prevent the recruitment of Proline Acid Rich (PAR) transcription factors to pro-apoptotic genes in colon cancer." (PMID 38356719, 2024).
esophageal cancer (2 papers, 2014 to 2016). A primary or metastatic malignant neoplasm involving the esophagus. "The esophageal cancer cells were negatively isolated by MACS and subjected to RT-qPCR to detect the expression of circadian clock molecule mRNA, including NFIL3, Per1, Per2, Bmal1, Cry1, Cry2, Clock and Npas2." (PMID 26898709, 2016).
osteosarcoma (2 papers, 2019). A usually aggressive malignant bone-forming mesenchymal neoplasm, predominantly affecting adolescents and young adults. "Therefore, we assume that NFIL3 is closely associated with the morbidity, development, and prognosis of osteosarcoma." (PMID 31886210, 2019). "NFIL3 is potential to become a new target for development of novel treatment strategies of osteosarcoma." (PMID 31886210, 2019). "NFIL3 is highly expressed in osteosarcoma tissues and thus promotes the proliferation, migration, and invasion of osteosarcoma cells." (PMID 31886210, 2019). "The expression of NFIL3 in osteosarcoma tissues was analysed via RT-PCR and immunohistochemistry staining." (PMID 31886210, 2019). "The wound healing assays and transwell migration and invasion assays showed that NFIL3 acts as an oncogene and boosts the migration and invasion of osteosarcoma cells." (PMID 31886210, 2019). "In this study, we meant to probe the function of NFIL3 in osteosarcoma proliferation, migration, and invasion." (PMID 31886210, 2019). "Immunohistochemical staining analysis was used to further confirm this result, and 15 of 20 osteosarcoma tissues highly expressed NFIL3." (PMID 31886210, 2019). "NFIL3 is overexpressed in osteosarcoma tissues; 15 of the 20 osteosarcoma tissues analysed highly expressed NFIL3." (PMID 31886210, 2019). "Transwell migration and invasion assays showed that overexpressed NFIL3 significantly promoted migration and invasion of osteosarcoma cells, whereas knockdown of NFIL3 noticeably inhibited the migration and invasion of osteosarcoma cells (P < 0.05)." (PMID 31886210, 2019). "After a series of studies, we provide the first evidence that the expression levels of NFIL3 are consistently increased in osteosarcoma tissues." (PMID 31886210, 2019). "It was found that overexpression of NFIL3 promoted the proliferation, migration, and invasion of osteosarcoma cell line MG-63 and SaOS2." (PMID 31886210, 2019). "To further study the relationship of NFIL3 with osteosarcoma, we performed cytological experiments, including RT-PCR, wound healing assays, migration and invasion assays, cell cloning assays, cell proliferation assays, and other assays." (PMID 31886210, 2019). "In order to elucidate the function of NFIL3 in osteosarcoma, we performed cell growth assays and colony formation assays to explore the role of NFIL3 in proliferation in osteosarcoma cells." (PMID 31886210, 2019). "When the NFIL3 gene was knocked out, the proliferation ability, invasion ability, and metastasis ability of osteosarcoma cells were significantly inhibited." (PMID 31886210, 2019). "This is a novel phenomenon that suggests NFIL3 has potential to become a novel target for the immunotherapy and targeted therapy of osteosarcoma which will be a new direction for our future research." (PMID 31886210, 2019). "NFIL3 is highly expressed in osteosarcoma tissues, thus promoting the proliferation, migration, and invasion of osteosarcoma cells." (PMID 31886210, 2019). "It was found that NFIL3 was highly expressed in human osteosarcoma tissues and adjacent tissues." (PMID 31886210, 2019). "We believe that NFIL3 will be a novel target for development of treatment strategy of osteosarcoma; the underlying mechanism was not further elucidated in this article, but it will be determined in future studies." (PMID 31886210, 2019). "For the first time, we reveal the phenomenon of high NFIL3 expression in osteosarcoma and peritumoural tissue and by immunohistochemical and cytological experiments, further confirmed that NFIL3 is a crucial factor in the occurrence, development, and metastasis of osteosarcoma." (PMID 31886210, 2019). "NFIL3 promotes cell proliferation, invasion, and migration of osteosarcoma cells ex vivo." (PMID 31886210, 2019). "NFIL3 may become a new target for the treatment of osteosarcoma." (PMID 31886210, 2019). "In addition, NFIL3 promoted the migration and invasion of osteosarcoma cells (P < 0.05)." (PMID 31886210, 2019).
osteosarcoma (continued). "The expression level of NFIL3 was higher in osteosarcoma tissues than in matched nontumour tissues." (PMID 31886210, 2019).